OSR1 (odd-skipped related transcription factor 1)
Diseases named in the same sentence as OSR1 in open-access papers (continued):
Sharing a sentence is not in itself a finding about the gene and the disease.
ovarian carcinoma (2 papers, 2023 to 2025). A malignant neoplasm originating from the surface ovarian epithelium. "Supporting evidence from ovarian cancer studies further corroborates the prognostic value of OSR1 downregulation." (PMID 40692711, 2025). "The low OSR1 expression rate in the ovarian cancer group was notably higher than the normal ovarian group (P < 0.0001)." (PMID 37642735, 2023). "Immunohistochemical staining of paraffin-embedded sections was conducted to assess the OSR1 expression in patients with ovarian cancer." (PMID 37642735, 2023). "Our prior findings indicated that OSR1 expression was markedly lower in 30 fresh OC samples compared to 20 normal ovarian tissue samples, and its overexpression could impede ovarian cancer cell proliferation while promoting apoptosis." (PMID 37642735, 2023). "Immunohistochemistry was utilized to evaluate OSR1 expression in patients with ovarian cancer." (PMID 37642735, 2023). "Whether the downregulation of OSR1 expression in ovarian cancer occurs through the same mechanism warrants further investigation." (PMID 37642735, 2023). "Our study is the first to investigate the clinical implication of OSR1 in ovarian cancer." (PMID 37642735, 2023). "The mechanism through which OSR1 regulates ovarian cancer (OC) progression remains unclear." (PMID 37642735, 2023). "We gathered the clinicopathological features and survival data of the 86 ovarian cancer patients, and the results indicated a negative relationship between OSR1 expression and FIGO stage, histological differentiation." (PMID 37642735, 2023). "NF-κB pathway constitutive activation is associated with poor differentiation, tumor invasion, chemoresistance, late FIGO stage, and poor OS in OC.The downstream signaling pathways involved in the regulation of ovarian cancer pathogenesis by OSR1 have not been reported yet." (PMID 37642735, 2023).
prostate tumor (2 papers, 2013 to 2022). "Intriguingly, PtenLoxP/LoxP:Osr1-Cre mice develop high-grade prostatic intraepithelial neoplasms (PINs) as early as 4-weeks of age and prostatic tumors after 12-months of age." (PMID 23308230, 2013). "Intriguingly, PtenLoxP/LoxP:Osr1-Cre mice develop high-grade prostatic intraepithelial neoplasms (PINs) with high penetrance as early as one-month of age, and locally invasive prostatic tumors after 12-months of age." (PMID 23308230, 2013). "Castration of PtenLoxP/LoxP:Osr1-Cre mice shows no significant regression of prostate tumors, although a shift of AR staining from the nuclei to cytoplasm is observed." (PMID 23308230, 2013). "Castration of PtenLoxP/LoxP:Osr1-Cre mice shows no significant regression of prostate tumors, although a shift of androgen receptor (AR) staining from the nuclei to cytoplasm is observed in Pten null tumor cells of castrated mice." (PMID 23308230, 2013).
renal agenesis (2 papers, 2016 to 2023). Renal agenesis (RA) is a form of renal tract malformation characterized by the complete absence of development of one or both kidneys (unilateral RA or bilateral RA respectively), accompanied by absent ureter(s). "In keeping with its primordial involvement in organogenesis, previous studies showed that most mouse embryos homozygous for an Osr1 null mutation (Osr1–/–) die very early, between E11.5 and E12.5, due to multiple anomalies, including renal agenesis and severe cardiac defects." (PMID 37847567, 2023).
steatosis (2 papers, 2021 to 2022). Increased lipid within the cytoplasm of cells. "When comparing the total area of steatosis between male mouse groups, Osr1 heterozygous mice presented with statistically greater (p<0.01) lipid accumulation." (PMID 35657825, 2022). "When compared to the WT group, Osr1 heterozygous mice had significantly more steatosis." (PMID 35657825, 2022). "In the current study, our results could not reveal if increased liver inflammation in the Osr1+/- mice is a cause or a consequence of the steatosis, thus it is unclear if the worsened steatosis or the enhanced hepatic inflammation is the driving force for NAFLD progression." (PMID 35657825, 2022). "The Osr1 mice, regardless of sex, exhibited more severe steatosis compared to WT." (PMID 35657825, 2022).
acute myeloid leukemia (1 paper, 2023). Acute myeloid leukemia (AML) is a group of neoplasms arising from precursor cells committed to the myeloid cell-line differentiation. "The abnormal expression of LGR5 in acute myeloid leukemia cells counteracts the effects of OSR1 overexpression, resulting in reduced cell survival and proliferation." (PMID 37627077, 2023). "Silencing OSR1 has been demonstrated to enhance the proliferation of acute myeloid leukemia cells while simultaneously suppressing cell death." (PMID 37627077, 2023).
asthma (1 paper, 2022). "The other two DMPs -cg00456326 in the TSS1500 of OSR1 and cg20259981 in the TSS1500 of ST18- have been associated with atherosclerosis and Down syndrome and with asthma, respectively." (PMID 35836279, 2022).
Cerebral ischemia (1 paper, 2022). Restriction of arterial blood supply to the brain associated with insufficient oxygenation to support the metabolic requirements of the tissue. "In fact, cerebral ischemia gives rise to NKCC1 phosphorylation by activating WNK/SPAK/OSR1 pathway and increases its activity, and inhibition of NKCC1 can reduce tissue damage, neuronal death, edema, and neurological defects." (PMID 35871268, 2022).
colorectal adenocarcinoma (1 paper, 2025). The most common type of colorectal carcinoma. "Similarly, Osr1 has been implicated in cell cycle arrest and apoptosis in other contexts, such as colorectal adenocarcinoma." (PMID 40276524, 2025).
developmental delay (1 paper, 2016). "One explanation for the fertility phenotype is that there is a developmental delay in OSR1+/− males, but we observed no such developmental delay." (PMID 27853306, 2016).
glioblastoma (1 paper, 2020). The most malignant astrocytic tumor (WHO grade IV). "WNK1 and 3 and their regulation of OSR1/SPAK and NKCC1 are essential for glioblastoma cell migration." (PMID 33604334, 2020).
Insulin resistance (1 paper, 2022). Increased resistance towards insulin, that is, diminished effectiveness of insulin in reducing blood glucose levels. "Although the cg00456326 DMP is novel, the OSR1 gene has previously been found associated with both insulin resistance and T2D in Europeans." (PMID 35836279, 2022). "Further studies are needed to better understand the potential role of the OSR1 gene in insulin resistance in African Americans." (PMID 35836279, 2022). "In the GWAS catalog, we found out that genetic variants annotated to HOXA5, OSR1 and ST18 were not independently related to insulin resistance traits." (PMID 35836279, 2022).
liver cancer (1 paper, 2022). An epithelial or non-epithelial malignant neoplasm that arises from the liver.
liver fibrosis (1 paper, 2025). "Wt1+ fibroblasts displayed distinct expression of genes, such as Scara5, Fbln2, Adgrd1, and Osr1 (encoding the odd-skipped related transcription factor 1) that has been linked to liver fibrosis, and mesenchymal collagen production (Fig. EV3E)." (PMID 40954217, 2025).
lung carcinoma (1 paper, 2023). "Similarly, OSR1 expression is reduced in lung cancer and is linked to lower histological differentiation." (PMID 37642735, 2023). "Additionally, OSR1 suppresses the Wnt/β-catenin pathway by upregulating GSK3 expression and inhibiting SOX9 expression, which reduces lung cancer invasion and proliferation." (PMID 37642735, 2023).
lymphedema (1 paper, 2024). Excess fluid collection in tissues, causing swelling. "Impaired lymphatic vasculature assembly in embryonic lymph node anlage and back lymphedema found in Osr1-deficient embryos indicates a more general role of Osr1+ mesenchymal cells in lymphatic vasculature formation." (PMID 39221968, 2024).
male infertility (1 paper, 2016). The inability of the male to effect fertilization of an ovum after a specified period of unprotected intercourse. "Collectively, these results indicate that an insufficiency of both OSR1 and SPAK in SCs resulted in impaired expression and phosphorylation of NKCC1 in testes, contributing to male infertility with impaired spermatogenesis." (PMID 27853306, 2016).
potassium deficiency (1 paper, 2025). A condition due to decreased dietary intake of potassium, as in starvation or failure to administer in intravenous solutions, or to gastrointestinal loss in diarrhea, chronic laxative abuse, vomiting, gastric suction, or bowel diversion. "First reported over a decade ago, WNK bodies were initially described as punctate clusters of the WNK-SPAK/OSR1 pathway that form in the DCT during potassium deficiency." (PMID 40493421, 2025). "Our analyses in KO mice demonstrated that during potassium deficiency, KS-WNK1 drives WNK body formation, amplifies NCC phosphoactivation, and increases WNK4-SPAK/OSR1 pathway expression." (PMID 40493421, 2025).
prostatic adenocarcinoma (1 paper, 2022). "Development of HGPIN and prostatic adenocarcinoma lesions in Osr1-Cre-driven hARtg transgenic mice but not in previous AR transgenic models regulated by the PB promoter implicates the critical role of prostatic Osr1-lineage cells in prostate tumorigenesis." (PMID 35902588, 2022).
schwannoma (1 paper, 2022). A benign, usually encapsulated slow growing tumor composed of Schwann cells. "To verify this result, we detected OSR1 expression in clinical samples of GIST, gastrointestinal leiomyoma and schwannoma." (PMID 36076237, 2022).
tongue cancer (1 paper, 2023). A malignant neoplasm affecting the tongue. "In tongue cancer tissue, OSR1 expression is decreased, and it is even lower in metastatic cases compared to non-metastatic ones." (PMID 37642735, 2023).
tongue squamous cell carcinoma (1 paper, 2021). A squamous cell carcinoma that arises from the tongue. "Interestingly, a recent study on tongue squamous cell carcinoma reported that Osr1 inhibited tumor cell migration and invasion by obstructing the NF-κB pathway." (PMID 33005011, 2021).
tumor (20 papers, 2013 to 2025). "A strong positive association was identified between OSR1 expression and tumor-infiltrating immune cells, particularly NK cells, DCs, and T cells." (PMID 40692711, 2025). "Collectively, these results demonstrate that OSR1 upregulation inhibits malignant tumor progression in vivo." (PMID 40692711, 2025). "Tumor growth was significantly suppressed in the OSR1 overexpression group, as evidenced by reduced tumor volume and weight relative to controls." (PMID 40692711, 2025). "Histological examination through H&E staining and immunohistochemistry of tumor sections indicated a reduction in tumor malignancy following OSR1 overexpression." (PMID 40692711, 2025). "The experimental results were consistent with database-derived observations, confirming the inhibitory role of OSR1 in tumor proliferation." (PMID 40692711, 2025). "In renal cell carcinoma, OSR1 acts as a tumor suppressor by attenuating cellular invasiveness and proliferation." (PMID 40692711, 2025). "The dysregulation of WNK-SPAK/OSR1 signaling, influenced by factors such as DHT, has been linked to tumor growth, metastasis, and angiogenesis." (PMID 38732080, 2024). "Odd-skipped related 1 (OSR1) has been reported as a tumor suppressor gene in various malignant tumors." (PMID 37642735, 2023). "Here, we demonstrate that a subpopulation of prostatic Osr1 (odd skipped-related 1)-lineage cells functions as tumor progenitors in prostate tumorigenesis." (PMID 35902588, 2022). "Co-staining of hARtg and mGFP were also revealed in both atypical and tumor cells, demonstrating their origin deriving from Osr1-expressing cells." (PMID 35902588, 2022). "Our results support the working model that the WNK1–SPAK/OSR1 axis is indeed involved in tumor-induced angiogenesis in both cancer cells and endothelial cells." (PMID 36292952, 2022). "In lung cancer (LC), the Akt-WNK1-SPAK/OSR1 axis is activated by factors in the tumor microenvironment (TME)." (PMID 36123332, 2022). "To explore the underlying mechanism by which OSR1 exerts tumor suppressive function in RCC, we performed RNA-Sequencing analysis to identify genes that were differentially expressed in OSR1 knockdown ACHN cells and control ACHN cells." (PMID 28404905, 2017). "Our study suggested that OSR1 is a silenced tumor suppressor in specific RCC cell lines due to promoter methylation." (PMID 28404905, 2017). "OSR1 can function as a tumor suppressor via inhibition of invasion and proliferation in RCC cells, possibly via upregulating tumor suppressor genes and downregulating oncogenes." (PMID 28404905, 2017). "This tumor specific silenced pattern suggested that OSR1 was potential silenced by promoter methylation in a tumor specific manner." (PMID 28404905, 2017). "Of note, recent studies have shown tumor specific silencing of OSR1 by promoter methylation in gastric and lung cancer." (PMID 28404905, 2017). "qRT-PCR analysis for human transcript levels showed significant elevation of renal “stemness” and progenitor genes that mark the early renal lineage, including SIX2 and OSR1, compared to their primary tumour of origin." (PMID 23239665, 2013). "Hence, OSR1 exerts a tumor-suppressing effect by inhibiting the LGR5-mediated activation of JNK signaling." (PMID 37627077, 2023). "In summary, OSR1 is downregulated in OC and may be a potential indicator of tumor malignancy and prognosis and a possible therapeutic target." (PMID 37642735, 2023). "Among the genes screened out by ChIP-seq of GIST tumour samples and cell lines, OSR1 was hypothesized to bind to the c-KIT locus by ATAC sequencing." (PMID 36076237, 2022). "Our functional study suggested that OSR1 is a functional tumor suppressor in RCC." (PMID 28404905, 2017).
tumor (continued). "Enhanced Akt activity is observed in Pten null tumor cells of castrated PtenLoxP/LoxP:Osr1-Cre." (PMID 23308230, 2013). "Besides its role in development, OSR1 also serves as a vital tumor suppressor." (PMID 37642735, 2023). "Thus, our data indicate that OSR1 is a novel tumor suppressor gene in RCC." (PMID 28404905, 2017). "Current studies have confirmed that OSR1 is significantly downregulated in cancers, including lung, breast, colon, gastric, kidney, and tongue squamous cell carcinoma (TSCC), and is a tumor suppressor." (PMID 37642735, 2023). "In zebrafish models of CRC and HCC, treatment with WNK1-SPAK/OSR1 axis inhibitors WNK463 and Closantel significantly reduced the expression of CCND1 and MMP9, and inhibited tumor metastasis and angiogenesis." (PMID 36123332, 2022). "The expression of both hARtg and mGFP in atypical and tumor cells within HGPIN and PCa lesions demonstrate the critical role of transgenic AR in Osr1-lineage cells in inducing prostatic oncogenesis and promoting PIN and PCa development." (PMID 35902588, 2022). "Because WNK1 activates OSR1/SPAK, if the osr1a/osr1b or stk39 are involved in tumor-induced angiogenesis, they are supposed to be upregulated from 2 dpi to 3 dpi." (PMID 36292952, 2022). "Our findings from using WNK1 and OSR1/SPAK inhibitors support the notion that OSR1/SPAK acts downstream of WNK1 for tumor angiogenesis and tumor growth." (PMID 32131390, 2020). "For OSR1, hypermethylation was detected in 47/48 LAC cases compared to 1/31 tumor-adjacent normal lung samples." (PMID 27782156, 2016). "The OSR1 region demonstrated a remarkably high sensitivity and specificity, as we detected hypermethylation in 97.9% of the LAC tumors (n = 48) and only in 3.2% of the tumor-adjacent normal lung samples (n = 31)." (PMID 27782156, 2016). "Recent studies have revealed that the dysregulation of WNKs contributes to tumor growth, metastasis, and angiogenesis through complex mechanisms, especially through phosphorylating kinase substrates SPS1-related proline/alanine-rich kinase (SPAK) and oxidative stress-responsive kinase 1 (OSR1)." (PMID 36123332, 2022). "Multifunctional nanoparticle carriers loaded with VP can selectively kill tumor cells under photoexcitation, whereas non-photoactivated VP inhibits YAP, SPAK, and OSR1 by targeting their kinase domains in an ATP-dependent manner and the suppression is more obvious in the dark." (PMID 33178014, 2020).
cancer (17 papers, 2010 to 2025). A tumor composed of atypical neoplastic, often pleomorphic cells that invade other tissues. "A potential molecular target participating in lipid homeostasis and hepatic inflammation is the Odd-skipped related 1 (Osr1) gene, which plays a critical role in embryonic development as a cancer repressor gene." (PMID 37760534, 2023). "Previous studies have shown that OSR1 inhibits cancer development and progression through several signaling pathways." (PMID 37642735, 2023). "The activation of the Akt-WNK1-SPAK/OSR1 axis upregulates mesenchymal markers Snail and N-cadherin and downregulates epithelial markers E-cadherin, thus promoting cancer EMT." (PMID 36123332, 2022). "Odd skipped-related 1 (Osr1) is a novel tumor suppressor gene identified in several cancer cell lines." (PMID 36012464, 2022). "On the contrary, WNK1-activated OSR1 can phosphorylate Smad2/3 at residues Thr-220/179 and enhance their activity in cancer cells, which activates pro-EMT transcription factors and further promotes the expression of TGF-β1 in an autocrine manner." (PMID 36123332, 2022). "Methylation of CpG islands in Osr1 coding regions has been documented in multiple cancer cell lines." (PMID 33005011, 2021). "Knockdown of OSR1 in normal expressed cancer cell lines elevated invasion ability and cellular proliferation." (PMID 28404905, 2017). "Expression profile of genes involved in multiple cancer-related pathways was changed when OSR1 was downregulated." (PMID 28404905, 2017). "The involvement of those cancer related pathway indicated that OSR1 has functional role in tumorigenesis." (PMID 28404905, 2017). "RNA-Sequencing analysis showed that expression profile of genes involved in multiple cancer-related pathways was changed when OSR1 was downregulated." (PMID 28404905, 2017). "However, none of the studies thus far have considered alterations of relevant signaling through changes in biomolecular condensates mediated by aberrant activation of the WNK-SPAK/OSR1 cascade in cancer cells." (PMID 40643468, 2025). "Recently, OSR1 has been reported to regulate the onset and development of various cancers." (PMID 37642735, 2023). "Odd-skipped related 1 (Osr1) is a novel tumor suppressor gene in several cancer cell lines." (PMID 33005011, 2021). "Thus, our present study indicated that OSR1 is a novel TSG in RCC but is frequently silenced by promoter methylation in this cancer." (PMID 28404905, 2017). "Thus, our data indicate that OSR1 functions as a novel TSG in RCC but is frequently epigenetically silenced in this cancer." (PMID 28404905, 2017). "For promoter-associated CpG islands, a number of them, including those of NTF3, FGF, OSR1, HOXA6, NPY and WT1, have previously been reported as differentially methylated in other cancer types." (PMID 20051947, 2010).
genetic diseases (1 paper, 2020). "Components of the WNK-SPAK/OSR1 pathway: associated genetic diseases, and phenotype of knockout models." (PMID 33192599, 2020).